INS (insulin)
Diseases named in the same sentence as INS in open-access papers (continued):
Sharing a sentence is not in itself a finding about the gene and the disease.
Insulin resistance (continued). "Conversely, SIRT2 deletion induces muscle insulin resistance, while inhibiting SIRT2 improves insulin sensitivity in insulin-resistant muscle cells 28,140." (PMID 38904020, 2024). "As compared with T2DM—which occurs due to insulin resistance and shares a close link with metabolic syndrome —T1DM is an entirely different disorder that is hallmarked by the autoimmune destruction of insulin-secreting pancreatic islet beta cells." (PMID 38256693, 2024). "Animals on an MCD diet maintain or even improve insulin sensitivity, while humans with NAFLD often exhibit insulin resistance." (PMID 39000518, 2024). "The insulin resistance model (TNF-a and TNF-a+INS) showed an opposite behavior, i.e., a significant decrease of p-Akt and a significant increase of p-JNK." (PMID 39627194, 2024). "Aerobic exercise diminishes insulin resistance (p < 0.01) through the reduction in FBG (p < 0.01) and insulin concentrations, enhancing glucose tolerance (p < 0.01) and bolstering the capacity to react to hyperglycemia challenges at different intervals." (PMID 39458447, 2024). "Interaction between AGE and RAGE modulates intracellular cascade of biochemical reactions which inhibits insulin-induced GLUT-4 translocation and induces insulin resistance." (PMID 38672494, 2024). "Due to long-term insulin resistance, the function of islet cells in T2DM patients is gradually impaired, resulting in relatively insufficient insulin secretion, which has been proved by many studies." (PMID 39334959, 2024). "Both studies indicated that insulin resistance, measured by HOMA-IR, was an independent determinant of progression when adjusted for beta cell function, as measured by first-phase insulin release (FPIR)." (PMID 37914981, 2024). "Moreover, despite the significant reduction in serum insulin, the effect size was estimated to be small which may limit the interpretation of results for the effect of NS on serum insulin levels or the status of insulin resistance." (PMID 38178093, 2024). "The HOMA-IR value for NPD was within the insulin-sensitive range (<1.0), while the PD group had a significantly higher HOMA-IR value compared to the PD, which was in the range of significant insulin resistance." (PMID 38791468, 2024). "We also observed the insulin resistance index (HOMA-IR), an important index for assessing insulin sensitivity." (PMID 38429334, 2024). "This supports the role of insulin in regulating AKR1C3 expression, leading to hyperandrogenemia, which in turn results in hyperinsulinemia and insulin resistance, creating a vicious cycle as discussed in the review by Storbeck and O’Reilly." (PMID 39273637, 2024). "Given the complex interplay between insulin resistance, dyslipidemia, and cardiovascular health, DPP4 inhibitors offer a multifaceted approach to managing these conditions within the insulin–heart axis." (PMID 39337658, 2024). "HOMA mainly includes HOMA of insulin resistance (HOMA-IR), HOMA of insulin sensitivity (HOMA-IS), and HOMA of beta-cell function (HOMA-β), and is obtained by calculating the relationship between fasting insulin levels and blood glucose levels." (PMID 38969755, 2024). "Another commonly used parameter, homeostasis model assessment‐insulin resistance (HOMA‐IR), was usually calculated by blood glucose and insulin level." (PMID 38225901, 2024). "The third factor is classified as 'glucose metabolism', formed by glucose, homeostatic model assessment for insulin resistance (HOMA-IR), and the insulin sensitivity index (ISI)." (PMID 37861942, 2024). "Fasting blood glucose (FBG) increased by 40% (p < 0.0001), plasma insulin by 100% (p < 0.05), and HOMA-IR by 150% (p < 0.0004), indicating insulin resistance." (PMID 38927040, 2024). "There are diverse mechanisms that lead to insulin resistance, one of which involves KATP channels and their control of the insulin pathway in different tissues." (PMID 38612888, 2024).
Insulin resistance (continued). "The second method which is subphenotyping uses homeostatic model assessment (HOMA) for insulin sensitivity (IS) and beta cell function (BCF) because T2D is primarily characterised by beta cell dysfunction, insulin resistance, or a combination of both." (PMID 39217248, 2024). "Zhang and colleagues reported that physical exercise intervention ameliorates insulin resistance and improves SIRT6-mediated insulin signaling transduction in the liver of obese rats." (PMID 39372420, 2024). "Insulin resistance is generally accepted as having an HOMA-IR > 2, whilst hyperinsulinaemia is considered where the fasting plasma insulin is > 28.8 uIU/mL." (PMID 39062126, 2024). "Therefore, we speculate that applying incretin-based medications in PD models can promote insulin secretion, improve peripheral and central insulin resistance, stabilize mitochondrial function, enhance energy metabolism, and exert neuroprotective effects that stabilize dopamine homeostasis." (PMID 39719978, 2024). "The cohort had elevated mean fasting and 2-hour insulin concentrations and high HOMA-IR levels, indicating systemic insulin resistance." (PMID 38895640, 2024). "In T2D, prolonged hyperglycemia and insulin resistance often result in elevated levels of insulin and insulin-like growth factors (IGF), which activate the insulin/IGF signaling pathway." (PMID 39640975, 2024). "Thrombin stimulates insulin secretion through PAR3 and blocking the cleavage of PAR3 was expected to counteract insulin resistance and β-cell failure driven by excessive insulin secretion in T2DM." (PMID 39609876, 2024). "Older people with insulin resistance had a very different pattern of coupling between CBF and CMRGLC than the insulin sensitive groups, suggesting a failure of the coupling." (PMID 38914735, 2024). "Alternatively, homeostatic model assessment of insulin resistance (HOMA-IR) and TyG index were recently identified and proved to be reliable tools for insulin-resistant screening." (PMID 38658993, 2024). "Insulin levels, however, remained elevated in mice infused with BHB and resulted in an elevated HOMA-IR, indicating that insulin resistance is still present in these mice." (PMID 38553002, 2024). "Insulin resistance, a major contributing factor to T2DM, is defined as a physiological state in which tissues are insensitive to the action of insulin." (PMID 39050759, 2024). "Insulin resistance is a common feature of PCOS, in which the body has difficulty effectively utilizing insulin." (PMID 38276279, 2024). "Meanwhile in peripheral tissue, the misassembled SNAREs disturbed insulin-sensitive GLUT4 vesicle trafficking and resulted in insulin resistance and metabolic disorders in patients with PCOS." (PMID 38674428, 2024). "We highlight two phospholipase encoding genes, PLA2G12A and PLA2G6, which liberate arachidonic acid and improve insulin sensitivity, and VGLL3, a transcriptional co-factor that increases insulin resistance partially through enhanced adiposity." (PMID 39277575, 2024). "Given the important role of insulin resistance in PCOS pathogenesis, medications aimed at lowering insulin levels have emerged as potential treatments, with metformin being the most commonly prescribed drug." (PMID 38737668, 2024). "Interestingly, DGs and their targets protein kinase C (PKC) and protein kinase D (PKD) have been shown to regulate multiple critical cellular responses, which might be a plausible mechanism for inhibition of insulin signalling leading to hepatic insulin resistance." (PMID 38248836, 2024). "Psychological insulin resistance (PIR) refers to psychological barriers to the initiation and persistence of insulin therapy." (PMID 39036047, 2024). "In addition to HMB, insulin use, MS, hormonal use, and anemia were also strongly associated with CVD in our analysis of hospitalizations of young women indicating that iron deficiency, insulin resistance, and hormonal changes along with HMB are important factors of CVD risk." (PMID 38783294, 2024).
Insulin resistance (continued). "Psychological insulin resistance (PIR), which refers to the reluctance of diabetic patients to use insulin, is a frequently encountered clinical issue." (PMID 38803476, 2024). "Activin-A has been correlated with parameters of insulin resistance, such as homeostasis model assessment of insulin resistance (HOMA-IR) and fasting plasma insulin concentrations." (PMID 38396489, 2024). "Insulin interacts with INR to initiate the signaling pathway of insulin and improve insulin resistance." (PMID 38921004, 2024). "The short insulin tolerance test (SITT) is a simple and convenient method for estimating insulin resistance." (PMID 38905235, 2024). "Traditional measures like the homeostatic model assessment for insulin resistance (HOMA-IR) and the quantitative insulin sensitivity check index (QUICKI), both of which rely on fasting insulin levels, are limited by practical constraints and variability." (PMID 39872136, 2024). "A homeostatic model of insulin resistance (HOMA-IR) calculation showed insulin resistance in the AL group and improved insulin sensitivity in the TRF group." (PMID 38672595, 2024). "By overexpressing RBP4 in wild-type rats or injecting recombinant human RBP4, insulin resistance can be induced in rats, whereas RBP4 gene deletion can enhance insulin sensitivity." (PMID 39698033, 2024). "According to the measurements of insulin resistance—hyperinsulinemic euglycemic clamp test and HOMA-IR—both groups showed improved insulin sensitivity throughout the study." (PMID 39598143, 2024). "Because inflammation and insulin resistance are considered critical for NAFLD progression, signaling pathways, including insulin signaling cascades, the NF-κB signaling pathway, and the MAPK signaling pathway, have key roles in NAFLD." (PMID 39033101, 2024). "The Metabolic Score for Insulin Resistance (METS-IR) offers a promising and reliable non-insulin-based approach to assess insulin resistance and evaluate cardiometabolic risk." (PMID 38711979, 2024). "Insulin resistance, reflected by the HOMA-IR index, signifies weakened insulin sensitivity and inhibits insulin-regulated signaling pathways." (PMID 39281051, 2024). "HFD treatment also induced similar increases in fasting insulin levels and HOMA-IR, a measure of insulin resistance, in both groups, although it reached statistical significance only in the Nrf2+/+ group when compared to their SD controls." (PMID 38612986, 2024). "Obesity is associated with systemic low-grade inflammation, contributing to the development of insulin resistance, a key feature of T2DM, by disrupting insulin signaling and glucose metabolism." (PMID 39685707, 2024). "For the clinical diagnosis of insulin resistance, we used the HOMA IR index with the addition of glucose and the insulin area under the curve (AUC) for more precise results and statistical analyses." (PMID 38397951, 2024). "The results indicated a decrease in serum levels of FBS, insulin, cholesterol, triglyceride, LDL, and insulin resistance in the rats treated with CUR." (PMID 39759349, 2024). "The present study evaluated the effect of insulin, an insulin receptor antagonist, and a TLR4 inhibitor on behavioral deficits and insulin resistance induced by 6-hydroxydopamine (6-OHDA)." (PMID 39830652, 2024). "The Homeostasis Model Assessment of Insulin Resistance (HOMA-IR) is a commonly employed alternative, offering ease of use; however, this test cannot be used to diagnose people who are already undergoing insulin treatment." (PMID 38907271, 2024). "Due to their complexity and invasiveness, the metabolic score for insulin resistance (METS-IR) score was developed, a novel and more promising non-invasive tool for screening insulin sensitivity." (PMID 39469359, 2024). "Blood samples were collected to assess fasting glucose and insulin levels and calculate HOMA-IR (homeostasis model assessment of insulin resistance)." (PMID 38980569, 2024).
Insulin resistance (continued). "mKD mice exhibited enhanced glucose tolerance, insulin sensitivity and resilience to HFD-induced insulin resistance." (PMID 38216792, 2024). "Consistent with the increased hepatic insulin resistance, HFD-fed Ogg1-KO mice showed increased whole-body insulin resistance phenotype as evidenced by an increase in insulin levels as well as in the results of ITT." (PMID 39596235, 2024). "The HOMA Insulin Resistance index tended to increase, whereas the HOMA Insulin Secretion index increased significantly." (PMID 39765759, 2024). "The PGR group developed insulin resistance as indicated by the increased HOMA-IR (homeostasis model assessment insulin resistance) index calculated from fasting glucose and insulin." (PMID 39872217, 2024). "Increased visceral adiposity was reflected on the metabolic status, as the SFD group showed elevated serum levels of fasting glucose, fasting insulin, and HOMA-IR levels when compared to other groups indicating a state of insulin resistance." (PMID 39127712, 2024). "These included triglycerides, Homeostatic Model Assessment for Insulin Resistance (HOMA-IR; calculated using fasting blood glucose and insulin levels), high-density lipoprotein cholesterol (HDL-C) and low-density lipoprotein cholesterol (LDL-C)." (PMID 39606458, 2024). "We used the following indices to assess insulin resistance of different tissues, including HOMA-IR, hepatic-IR, Adipo-IR, and the Matsuda index for whole-body insulin sensitivity." (PMID 39175570, 2024). "Further, the insulin resistance KEGG pathway [hsa04931 involves various mechanisms contributing to altered glucose metabolism and insulin responsiveness." (PMID 39118009, 2024). "Insulin sensitivity was measured by frequently sampled intravenous glucose tolerance test (FSIVGTT), homeostasis model assessment of insulin resistance (HOMA-IR), and hyperinsulinemic euglycemic clamp in a subset of participants." (PMID 38919390, 2024). "Relevant studies have shown that IGF-1 not only reduces both serum insulin levels and normal blood glucose levels but also improves insulin resistance in patients with T2DM and worse severe insulin resistance." (PMID 38463527, 2024). "In recent years, SGBS cells have been applied to insulin resistance research (a total of 41 papers in PUBMED searching, using the key words “SGBS cells, insulin resistance”)." (PMID 39749015, 2024). "The High ATIR group also had the highest values for several parameters: glucose level at 120 min, IGT prevalence, areas under the curve for insulin and FFA during OGTT, and indices of insulin resistance (Matsuda index and HOMA-IR)." (PMID 39377071, 2024). "However, the insulin levels were sustained longer in OVX/HFHSD-fed female mice than in non-OVX/ND-fed female mice and non-OVX/HFHSD-fed female mice, suggesting that a combination of estrogen deficiency and HFHSD could lead to insulin resistance." (PMID 39337631, 2024). "IPA can significantly reduce fasting blood glucose and insulin levels in rats, as well as homeostasis model assessment of insulin resistance (HOMA-IR), improving insulin resistance." (PMID 38998662, 2024). "Insulin resistance in the brain, mimicking peripheral insulin resistance in T2DM, can result in hyperinsulinemia in the brain, creating an environment in which insulin competes with Aβ as a substrate for insulin-degrading enzyme (IDE)." (PMID 38255204, 2024). "The production of IL-1 disrupts insulin signaling and leads to the degradation of insulin receptor substrate-1 (IRS-1) by neutrophils, which has been shown to contribute to insulin resistance (IR)." (PMID 39119009, 2024). "Substantial alterations were observed in insulin resistance within the SPJ and SB groups, with a notable increase in insulin sensitivity." (PMID 39459564, 2024). "Accordingly, we demonstrate that PG treatment dramatically lowers insulin resistance in GKHFD rats, emphasizing the critical role that inflammation plays in regulating insulin sensitivity." (PMID 39125901, 2024).
Insulin resistance (continued). "They found fasting insulin and HOMA-IR (Homeostatic Model of Insulin Resistance) to be significantly higher in transgender women compared to both cisgender sexes." (PMID 38738018, 2024). "Determination of fasting insulin levels is essential in assessing the metabolic status of the patient, as in PCOS patients carbohydrate metabolism disturbance often manifests as insulin resistance." (PMID 38337532, 2024). "In humans and mice models, subjects with insulin resistance and obesity have decreased levels of IRS-1, IRS-2, and PI3K expression in several insulin-sensitive tissues, and of p42/p44 mitogen-activated protein (MAP) kinase in skeletal muscle." (PMID 39684905, 2024). "T1D is characterized by development of absolute insulin deficiency, typically of autoimmune origin, requiring lifelong insulin treatment while T2D is marked by relative insulin deficiency with insulin resistance and, at least initially, may respond to lifestyle or non-insulin agents." (PMID 38632329, 2024). "Serum insulin and HOMA analysis are standard methods to measure insulin resistance and beta cell function." (PMID 39683552, 2024). "Insulin resistance/sensitivity was determined using Quicki, HOMA-IR, MacAuley, Revised MacAuley, Bennetts, FIRI and insulin-to-glucose ratio." (PMID 38233797, 2024). "Research has shown that pro-inflammatory diets are significantly associated with elevated glucose metabolic indices, including fasting plasma glucose (FPG), fasting serum insulin (FSI), and the homeostasis model assessment of insulin resistance (HOMA-IR)." (PMID 39796481, 2024). "Increased expression levels of adiponectin mRNA and its receptor as an insulin sensitivity agent, followed by an enhancement of the pump mRNA levels and PGC‐1α, contribute to glycemic and insulin resistance control." (PMID 39479712, 2024). "The homeostasis model assessment of insulin resistance (HOMA-IR), based on FPG and insulin measurements, is considered the gold standard for evaluating insulin sensitivity." (PMID 39104819, 2024). "Linear regression analysis using the decrease in UACR values as the dependent variable demonstrated a positive linear relationship with the decrease in BMI, VFA, fasting insulin (FINS), and homeostasis model assessment of insulin resistance (HOMA-IR)." (PMID 38720150, 2024). "As a result, this contributed to the attenuation of insulin-induced IGF-R and IRS1 phosphorylation, leading to insulin resistance." (PMID 39128726, 2024). "Insulin resistance in T2DM, which leads to higher circulating levels of insulin, is known to play an active role in the pathophysiology of endothelial dysfunction." (PMID 39037711, 2024). "Metabolic score for insulin resistance (METS-IR) has emerged as a novel, non-insulin-based metric for evaluating IR and has gained attention from researchers in recent years." (PMID 39514584, 2024). "Under insulin resistance, BBR treatment improves insulin-mediated glucose transport in muscle tubes and GLUT4 translocation, promoting glucose uptake." (PMID 38957396, 2024). "In summary, adipokine markers contributing to insulin resistance, such as leptin, chemerin, FABP4, and RBP4, are typically elevated in GDM, whereas those contributing to insulin sensitivity, like adiponectin, are reduced in GDM." (PMID 39519218, 2024). "At the terminal experimental protocol, the obese group showed higher levels of serum insulin and HOMA‐IR compared to the control group, confirming the presence of insulin resistance in the obese group." (PMID 39610053, 2024). "Insulin resistance indices, such as homeostasis model assessment of insulin resistance (HOMA-IR) and quantitative insulin sensitivity check index (QUICKI) were calculated." (PMID 39622897, 2024).